IL33 (interleukin 33)
Diseases named in the same sentence as IL33 in open-access papers (continued):
Sharing a sentence is not in itself a finding about the gene and the disease.
allergic disease (continued). "Notably, a mix of anti-IL-33, anti-TSLP and anti-IL-25 prevented egg allergy induction and suppressed ongoing disease." (PMID 36660742, 2022). "The sensing of IL-33 by MCs induces the MyD88−TAK1−IKK2-dependent activation of p65/RelA and MAP-kinases, which mediate the production of pro-inflammatory cytokines and amplify FcεRI-mediated MC-effector functions and the resulting allergic reactions." (PMID 36142767, 2022). "In an ovalbumin-induced food allergy model, TSLP-induced food allergy was dependent on the presence of IL-33, but IL-33 driven allergy was independent of TSLP." (PMID 36660742, 2022). "As mentioned, the IL-33/ST2 axis can strongly accelerate the Th2 cell function, indicating that PPARG might be a potential target for the treatment of allergic diseases." (PMID 36003397, 2022). "As a result of emerging evidence, IL-25, IL-33, and TSLP are important mediators of inflammation during allergic disease and may prove to be key targets for therapeutic intervention." (PMID 35406669, 2022). "IL-33 has been described as a DAMP released from epithelial barrier tissues and perivascular regions of the lung to aid parasite clearance and contribute to allergy through the antigen-independent functions of type 2 innate lymphoid cells and Th2 cells." (PMID 35503257, 2022). "Release of TSLP, IL-33, IL-25 and GM-CSF is obviously not restricted to allergy; however, these cytokines mostly contribute to type 2 immune response through specific activation of dendritic cells." (PMID 34084159, 2021). "In addition to their well characterized role in mediating IgE-dependent allergic diseases, aberrant accumulation and activation of mast cells (MCs) is associated with many non-allergic inflammatory diseases, whereby their activation is likely triggered by non-IgE stimuli (e.g., IL-33)." (PMID 32814824, 2021). "The role of IL-25, IL-33 and TSLP in various allergic diseases has been studied for several years." (PMID 34301307, 2021). "Therefore, targeting IL-33/ST2 signaling in mast cells (or ILC2) represents an important strategy for the prevention and treatment of broad ranges of allergic diseases." (PMID 31804564, 2019). "We have previously reported the restoration of the epithelial barrier function by inhibiting the expression of key promoters of allergy (thymic stromal lymphopoietin [TSLP] and interleukin 33 [IL-33]), which contribute to the Th2 immune response observed in early AD9." (PMID 31767859, 2019). "This hyporesponsiveness of ILC2s did not occur when the basal ILC2 activity was maintained by IL-2 and IL-7 without IL-33, which is a strong inducer of allergy." (PMID 30683858, 2019). "In addition, the cytokines IL-33 and TSLP deserve specific attention here, due to their ability to activate mast cells and their known role in allergic disease." (PMID 29755466, 2018). "IL-33-expanded Tregs express ST2 and can be found in several immune and non-immune tissues exerting potent suppressor function in a variety of pathological conditions, such as autoimmunity, inflammation, transplantation, and allergy." (PMID 30483263, 2018). "IL-33 and ST2 may become novel molecular targets for the interference of allergic diseases in ocular surface." (PMID 29987222, 2018). "In this review, we will address the evidence for IL-33 and ST2 regulation over eosinophils and how this may contribute to allergic diseases." (PMID 28512632, 2017). "We hypothesized that AS-IV could regulate the key pro-allergic cytokines IL-33 and TSLP derived from ECs and as a consequence, inhibits the occurrence and development of allergic diseases." (PMID 27917896, 2016). "Therefore, IL-33 and ST2 play an important role in allergic diseases and various mucosal immune responses, suggesting the involvement of the IL-33/ST2 pathway in the pathogenesis of a large number of diseases, especially in the responses based on the Th2 type." (PMID 25032216, 2014).
allergic disease (continued). "IL-25, IL-33 and TSLP, which are produced by epithelial cells, have a shared biological activity to induce Th2 cytokines, suggesting involvement in the development of allergic diseases." (PMID 24205109, 2013). "IL-33, IL-25 and thymic stromal lymphopoietin (TSLP) are thought to share several roles in immune responses, such as induction of Th2 cytokines by Th2 cells, suggesting that these cytokines contribute to the development of allergic diseases." (PMID 24205109, 2013). "Basolateral challenge of the epithelium with HIS induced upregulation of pro-inflammatory cytokines as IL-6 and IL-8; however, other major cytokines involved in the allergic reaction (IL-25, IL-33, and TSLP) were not detectable in the epithelium with or without the addition of HIS." (PMID 38933682, 2024). "However, the roles and relationships of IL-33 and maternal di(2-ethylhexyl) phthalate (DEHP) exposure in the pathogenesis of later-developed childhood allergies remain unclear." (PMID 37545493, 2023). "Therefore, we suppose that IL-35 may be involved in allergic diseases by regulating the expression of TSLP, IL-33, and IL-25 from HNECs." (PMID 34899052, 2021). "The IL-33/ST2 pathway intervenes in the pathogenesis of Th2-related diseases, such as allergies, but could also exert some protective effects in other inflammatory pathologies, such as cardiovascular diseases and OP, mainly depending on genetics, disease duration, and the cytokine microenvironment." (PMID 33488605, 2020). "IL-33 is an epithelial cell-derived cytokine which signals through ST2, a receptor expressed by T cells, mast cells, DCs, basophils, eosinophils, and ILC2s29, and may be a key factor in the establishment of allergic disease in the skin and other sites." (PMID 28490737, 2017). "IL-33 needs the specific receptor ST2 (membrane-bound receptor) and Interleukin-1 receptor accessory protein heterodimer for its binding, which instigates the production of different types of cytokines and chemokines that have crucial roles in the exacerbation of allergic diseases and inflammation." (PMID 26425339, 2015). "Although it does not induce mast cell degranulation on its own, IL-33 increases the synthesis and therefore the amount of pre-stored granule mediators and augments IgE-mediated mast cell activation, and it can therefore potentially aggravate an allergic reaction." (PMID 31275312, 2019). "Thus in the allergy model, IL‐33 receptor signaling is essential for macrophage alternative activation but it's contribution to proliferation is not as direct as that seen with the reductionist IL‐33 delivery model." (PMID 27592711, 2016). "However, the elementary mechanisms of the release, expression, processing and regulation of IL‐33 in allergic diseases are not yet defined properly and may be crucial for the development of future therapeutic targets." (PMID 26425339, 2015). "IL-33 may play an important role in nonatopic allergy and idiopathic anaphylaxis." (PMID 22702477, 2012). "Increased expression of IL-33 and ST2 receptors has been observed in COPD; however, unlike in allergic diseases where it induces classic type 2 responses, the role and mechanisms are more complex." (PMID 38082335, 2023). "Specific associations were found when examining hematological effects but not for indicators of allergic diseases (i.e., IgE, TSLP and IL-33)." (PMID 34712855, 2021). "The crucial roles of the IL-33/ST2 axis in both IgE- and non-IgE–mediated allergic disease have been appreciated." (PMID 32595651, 2020). "Our data point to a synergistic action of TSLP and IL-33 on OX40L expression, as also more recently shown in a rhinovirus-mediated allergic reaction to aeroallergen, rather than an exclusive IL-33-mediated effect as previously suggested." (PMID 29896198, 2018). "This was rather surprising considering that IL-33 but not TSLP was previously indicated as having a critical, non-redundant role in allergy." (PMID 29896198, 2018).
allergic disease (continued). "Consistent with the importance of this pathway to allergic disease, NECs from allergic asthmatic patients were shown to express more DUOX-1 and IL-33 compared to non-asthmatic individuals." (PMID 28721208, 2017). "At variance with IL-2, IL-33 did not stimulate MC for IL-9/TGF-β production, a finding indicating a minor contribution of the IL-33/MC axis in promoting inflammatory allergy and pathology in response to the fungus." (PMID 28090087, 2017). "However, budesonide did not modulate the HDM-allergy induced AHR and increased the pulmonary tissue concentrations of IL-33." (PMID 25849971, 2015).
atopic dermatitis (139 papers, 2011 to 2026). "The histone deacetylase HDAC3 was shown to act as a transcriptional repressor of IL-33 in multiple sclerosis patients and in a model of Staphylococcus aureus-aggravated skin inflammation associated to atopic dermatitis." (PMID 40317004, 2025). "IL-33 is also involved in the regulation of chronic itch in CSU as well as in other skin diseases associated with severe pruritus (such as atopic dermatitis and parasitic diseases)." (PMID 39767672, 2024). "Numerous reports have illustrated the associations of IL-33, thymic stromal lymphopoietin factor, and cytokines with a range of conditions, including inflammation, asthma, and atopic dermatitis." (PMID 39061836, 2024). "Cytokines such as Thymic Stromal Lymphopoietin (TSLP), Interleukin-33 (IL-33), and Interleukin-4 (IL-4) are commonly expressed in atopic dermatitis and play roles in causing skin itching." (PMID 37762597, 2023). "The type 2 cytokines interleukins (IL)-4, IL-13, and IL-33 are central in the inflammatory pathogenesis of atopic dermatitis and implicated to play an additional role in itch sensation in murine models." (PMID 37868811, 2023). "IL-33 is implicated in type 2 immune response and the pathogenesis of allergic inflammatory diseases, such as atopic dermatitis." (PMID 35432341, 2022). "Previous studies have reported that the production of IL-33 increases in dry skin conditions resulting from allergic contact dermatitis, atopic dermatitis, and animal models of skin trauma caused by tape-stripping." (PMID 34925342, 2021). "For example, anti-IL-33 monoclonal antibodies have provided promising results in other skin conditions linked to inflammation, such as atopic dermatitis (AD)." (PMID 35053208, 2021). "We compared the response in single- and double-deficient IL-33−/−/ST2−/− C57BL/6J BomTac mice in the well-established calcipotriol-induced model of atopic dermatitis." (PMID 32296080, 2020). "We performed a three-step validation of commercially available and widely used human interleukin-33 enzyme-linked immunosorbent assay kit with serum samples from eight atopic dermatitis patients and five healthy controls." (PMID 26788445, 2016). "IL-33 is also an effective stimulator for skin ILC2s, and it is directly associated with skin inflammation and mouse model of atopic dermatitis." (PMID 26425339, 2015). "Notably, we found that higher levels of IL-33 genetic prediction were associated with a lower risk of atopic dermatitis, which seemingly contradicts prior research findings." (PMID 39055710, 2024). "The extract also reduced the expressions of cytokines such as TSLP, IL-33, and IL-4, which are commonly expressed in atopic dermatitis and play roles in causing skin itching, suggesting that the extract may have had a notable effect on reducing itching." (PMID 37762597, 2023). "In addition, aberrant IL-33 regulation is linked to chronic dermatoses like atopic dermatitis, psoriasis, and urticaria, whereby several in vivo models proved IL-33′s contribution to the respective pathologies." (PMID 33808264, 2021). "In humans, IL-33 has been implicated in allergic inflammation such as asthma and atopic dermatitis." (PMID 28702024, 2017). "Moreover, secondary metabolites isolated from traditional folk medicines that target IL-33 may hold significant value in the investigation of their relationship with the IL-33/ST2 signaling pathways implicated in atopic dermatitis." (PMID 39061836, 2024). "Silencing of miR-155-5p in atopic dermatitis mouse model reduced both the thickening of the epidermis and the expression of T helper type 2 (Th2) immune response-associated cytokines, thymic stromal lymphopoietin and interleukin-33, attenuating the overall allergic inflammation." (PMID 38562669, 2024). "This review, therefore, aims to assess the IL-31/IL-33 axis in atopic dermatitis, highlight existing uncertainties, and emphasize the need to develop biomarker and endotype-based therapeutic strategies targeting this pathway." (PMID 41155460, 2025).
atopic dermatitis (continued). "Biologics targeting IL-33 (e.g., Etokimab, Tozorakimab) have entered testing in atopic dermatitis, with early proof-of-concept data suggesting reduced disease activity and pruritus, including a significant reduction in neutrophil skin infiltrates." (PMID 41156043, 2025). "Interleukins IL-4, Il-5, IL-10, IL-13 and IL-33 play an important role in atopic dermatitis patients." (PMID 40771803, 2025). "IL-33 antagonists have shown a favorable safety profile in clinical trials for atopic dermatitis, although a single adverse event of venous thrombosis was reported." (PMID 41156043, 2025). "In atopic dermatitis patients, high IL-33 serum levels are positively correlated with the severity of atopic dermatitis." (PMID 38607023, 2024). "Etokimab was also used in clinical trials to assess the efficacy of anti-IL-33 therapy in atopic dermatitis." (PMID 38672221, 2024). "IL-33 is highly expressed in the skin and increases in inflammatory skin lesions in atopic dermatitis, psoriasis, and scleroderma." (PMID 38607023, 2024). "Many polyphenols, including curcumin, baicalin, and quercetin, have been found to inhibit the production of TSLP and IL-33 in atopic dermatitis mice models and human keratinocyte models of the disease." (PMID 38931338, 2024). "It has been shown that the expression of IL‐33 is elevated in allergic inflammation such as in atopic dermatitis and gastrointestinal inflammation." (PMID 39654685, 2024). "The inhibition of HDAC3 by butyrate leads to a decrease in IL-33 expression and subsequently alleviates skin inflammation in a mouse model resembling atopic dermatitis." (PMID 38235133, 2023). "IL-33 and IL-37 are also deeply involved in the pathogenesis of inflammatory skin diseases such as atopic dermatitis (AD) and psoriasis." (PMID 37834081, 2023). "Calcitriol administration attenuated the expression of Il13 and Il33 in the skin of NC/Nga mice with atopic dermatitis compared to vehicle-treated mice." (PMID 37298299, 2023). "We observed an increased mRNA expression of type 2 inflammatory mediators, including interleukin-4 (Il4), Il13, and Il33, in the skin of NC/Nga mice with atopic dermatitis compared with control mice." (PMID 37298299, 2023). "The expression of Il4, Il13, and Il33 was increased in the skin of NC/Nga mice with atopic dermatitis, while calcitriol application decreased Il13 and Il33 mRNA expression." (PMID 37298299, 2023). "Cutaneous afferent neurons express receptors interleukins (IL)-4, IL-13, and IL-33, which are type 2 cytokines that are elevated in atopic dermatitis." (PMID 37868811, 2023). "In the skin, ILC2-derived IL-5 is implicated in the strong eosinophil infiltrate observed in an IL-33 transgene-driven model of atopic dermatitis in mice." (PMID 38030609, 2023). "IL-33, which induces atopic dermatitis-like inflammation in mouse skin and is overexpressed in atopic dermatitis skin samples, can also be activated by environmental proteases, potentially exacerbating the response in atopic dermatitis." (PMID 38067173, 2023). "Etokimab (ANB020) is an anti-IL-33 humanized monoclonal antibody, which was assessed in adults with moderate-to-severe atopic dermatitis." (PMID 37509136, 2023). "The keywords selected for our searching process were “dysbiosis”, “IL-31”, “IL-33”, “IL-33/31 axis” and “microbiota” combined with “atopic dermatitis” and “psoriasis”." (PMID 37509136, 2023). "Elevated levels of IL-33 are found in skin lesions and in serum of patients with atopic dermatitis, whereas the average concentration of IL-33 in serum can be up to 10 times higher than in healthy individuals." (PMID 36904070, 2023). "Recent research has highlighted the role of interleukin-33 (IL-33) in modulating skin inflammatory cascades and its potential as a therapeutic target for atopic dermatitis." (PMID 37798647, 2023).